PIK3CA (phosphatidylinositol-4,5-bisphosphate 3-kinase catalytic subunit alpha)
Diseases named in the same sentence as PIK3CA in open-access papers (continued):
Sharing a sentence is not in itself a finding about the gene and the disease.
bladder cancer (88 papers, 2010 to 2025). "PIK3CA upregulation has been implicated in bladder cancer by promoting cell growth and regulating metastasis." (PMID 41342186, 2025). "At the genomic level, both sets of PDOs harbor common mutations associated with bladder cancer, such as PIK3CA, FGFR3, and RB1." (PMID 39921252, 2025). "Studies have shown that in bladder cancer, activation of this pathway is mainly associated with the loss of PTEN (phosphatase and tensin homolog) or PIK3CA gene mutations, and is more common in high-grade bladder cancer." (PMID 39911393, 2025). "Our study revealed that PIK3CA mutations are associated with a low risk of bladder cancer recurrence cancer." (PMID 39768623, 2024). "In vitro studies showed bladder cancer cells with mutations in PIK3CA were sensitive to pictilisib compared to wild-type cell lines." (PMID 39768623, 2024). "Concerning the entire population of patients with bladder cancer, the effect of the PIK3CA mutation with a 95% probability will be beneficial, with the HR range of 0.11–0.62." (PMID 39768623, 2024). "In this study, we showed that PIK3CA mutations are associated with a reduced risk of bladder cancer recurrence in patients from the Central European population." (PMID 39768623, 2024). "TERT gene mutations in bladder cancer tissue were observed in approximately 67% of cases and PIK3CA gene mutations in approximately 20%16,17." (PMID 37945655, 2023). "In another study, it was reported that PIK3CA gene mutation was associated with immunity in bladder cancer, and its inhibitor increased the sensitivity to PD1 blockade for mutant-type patients." (PMID 35642038, 2022). "In this context, we have evaluated the mutational status of PIK3CA and AKT1genes in bladder cancer biopsies and matched urines, and assess their use as anon-invasive molecular biomarker for patients ́ diagnosis and monitoring." (PMID 35317488, 2022). "In a prospective study of bladder cancer, mutations of the PIK3CA and AKT1 genes, the main players in the PI3K-AKT-mTOR signalling pathway (which plays a significant role in cell growth, proliferation, and survival), were examined." (PMID 35955727, 2022). "Many studies have shown that the onset and progression of bladder cancer are related to the PIK3CA gene, and its mutations have been detected in in bladder cancer cases with different stages and grades." (PMID 33344221, 2020). "In a humanized mouse model of bladder cancer with PIK3CA mutation, the treatment of BKM120(a pan-PI3K inhibitor) increases the expression of chemokines and immune genes." (PMID 33585182, 2020). "Either the inactivation of PTEN and TSC1/2 or activation of mutations of PIK3CA are commonly observed in advanced bladder cancer and are associated with worse outcomes." (PMID 32414171, 2020). "In particular, the co-occurrence of TSC1 and PIK3CA or PTEN mutations has been reported in bladder cancer." (PMID 31258848, 2019). "In particular, a subset of mTOR pathway alterations have been shown to occur in bladder cancer, such as mutations in PIK3CA gene, which culminates with increased mTOR signaling and bladder cancer cells resistance to apoptosis." (PMID 26569621, 2015). "Higher levels of PIK3CA expression were associated with worse prognosis in bladder cancer." (PMID 41342186, 2025). "Among Asian patients, PIK3CA E545K mutations were less frequent in bladder cancers." (PMID 38297963, 2024). "Therefore, we investigated the usefulness of TERT and PIK3CA mutations as blood biomarkers for bladder cancer." (PMID 37945655, 2023). "Remarkably, PIK3CA mutations have been found in all human cancers and are especially predominant in endometrial, breast, and bladder cancers, as well as Klippel–Trenaunay syndrome, which is a condition under the umbrella of PIK3CA-related overgrowth spectrum diseases." (PMID 37761256, 2023).
bladder cancer (continued). "The previous study reported mutations in the receptor FGFR3 and protein PIK3CA in bladder cancer." (PMID 36430344, 2022). "A recent animal study showed that buparlisib could significantly inhibit tumor growth and promote infiltration of human CD45+ cells and CD3+ T cells in humanized mice xenografted with PIK3CA-mutated human bladder cancer cells." (PMID 35326708, 2022). "Moreover, earlier studies revealed that the bladder cancer cell line TCCSUP, containing the PIK3CA E545K mutation, was more sensitive to the small-molecule inhibitor pictilisib than wild-type cells in a patient-derived xenograft mouse bladder cancer model." (PMID 35402614, 2022). "The presence of specific SNP on the level of PIK3CA was related with bladder cancer risk." (PMID 31665050, 2019). "In bladder cancer, PIK3CA mutations had previously been associated with low grade and stage tumors." (PMID 21072204, 2010). "However, no data exist regarding the prognostic value, in terms of recurrence-free, progression-free and disease-specific survival, of RAS and PIK3CA mutations in bladder cancer either alone or in combination with other alterations." (PMID 21072204, 2010). "Specifically, knockdown of PIK3CA was found to substantially inhibit cell proliferation, whereas overexpression of PIK3CA promoted bladder cancer cell growth, migration, invasion, and metastasis." (PMID 41342186, 2025). "Bladder cancer (BC) has some frequent mTOR alterations, with the most common mutations occurring in the TSC1 and PIK3CA genes, as well as copy number alterations affecting the PIK3CA gene." (PMID 39258533, 2025). "It seems further studies are needed on the PIK3CA gene to determine its significance in bladder cancer." (PMID 39768623, 2024). "CUX1 stimulates the transcription activity of PIK3CA in bladder cancer cells via direct interaction with the binding site of the PIK3CA promoter." (PMID 37627900, 2023). "For example, both PIK3CA and SYNE1 were mutated in around 22% of bladder urothelial carcinoma (bladder cancer) samples." (PMID 37624931, 2023). "Genetic mutations in the telomerase reverse transcriptase (TERT) gene and phosphatidylinositol-4,5-bisphosphate 3-kinase catalytic subunit alpha (PIK3CA) gene are prevalent in bladder cancer." (PMID 37945655, 2023). "The present study was planned to evaluate the mutational status of PIK3CA and AKT1 genes in bladder cancer patients and to assess the association between these mutations and patients ́ clinico-pathological features." (PMID 35317488, 2022).
bladder cancer (continued). "Recent bladder cancer studies have shown that genetic mutations in bladder epithelial cells frequently occur in FGFR3, PIK3CA, and RAS (all associated with RAS signaling networks)." (PMID 34234808, 2021). "The most frequently mutated genes in the chemo-naïve samples were well-established bladder cancer–associated genes: FGFR3 (70%), KMD6A (47%), PIK3CA (38%), KMT2D (26%), and ARID1A (23%)." (PMID 34934968, 2021). "Our study showed that PIK3CA is up-regulation in bladder cancer and promoted the proliferation, migration, invasion and angiogenesis of bladder cancer in vitro." (PMID 33344221, 2020). "Restoration of PIK3CA overexpression reversed the inhibitory effect on bladder cancer cell growth in vitro." (PMID 33344221, 2020). "PIK3CA immunoreactivity was notably higher in older patients with bladder cancer (P = 0.045), with more advanced clinical stage (P = 0.016), and higher rate positive lymph node metastasis (P = 0.031)." (PMID 33344221, 2020). "In summary, we determined that CUX1 is a vital TF of PIK3CA, regulating its expression and resulting changes in cellular functions in bladder cancer cells." (PMID 33344221, 2020). "In the current study, we revealed that PIK3CA is overexpressed in bladder cancer tissues, and PIK3CA participates in the proliferation, migration, and invasion of bladder cancer cells." (PMID 33344221, 2020). "Although the functional role of PIK3CA in EMT has been investigated in several cancers, there are only a few reports in bladder cancer demonstrating involvement of PIK3CA in the process of EMT." (PMID 33344221, 2020). "In summary, our study demonstrates for the first time that PIK3CA is overexpressed in bladder cancer, and is regulated by the transcription factor CUX1." (PMID 33344221, 2020). "Overly expressed PIK3CA promoted growth, migration, invasion, and metastasis of bladder cancer cells and knockdown of PIK3CA had the opposite effect." (PMID 33344221, 2020). "IHC assay indicated that PIK3CA was located in the cytoplasm of bladder cancer cells, and displayed that PIK3CA protein was detected in 44/56 (78.6%) bladder cancer cases and with a higher positive rate than normal cases (P = 0.002)." (PMID 33344221, 2020). "Colon and bladder cancer cells with KRAS mutation are resistant to AZD5363, although accompanied by coincident PIK3CA mutations." (PMID 32194423, 2020). "In contrast, our study claimed that the expression of PIK3CA is regulated by CUX1 in bladder cancer." (PMID 33344221, 2020). "PIK3CA gene alteration and PIK3CA upregulation are frequent events for bladder cancer which promotes bladder cancer cell proliferation, invasion, and metastasis." (PMID 33344221, 2020). "Here, we propose a model of CUX1-PIK3CA-EMT oncoprotein axis, to illustrate how PIK3CA is activated and contributes to bladder cancer progression and metastasis." (PMID 33344221, 2020). "Among the candidate molecules associated with urothelial differentiation are KRT20, a well established luminal marker, and FGFR3, STAG2, and PIK3CA—three major bladder cancer genes commonly altered in luminal tumors." (PMID 32635360, 2020).
bladder cancer (continued). "To further probe the potential effects of PIK3CA in bladder cancer cells, we first transfected bladder cancer cell lines EJ and T24T with a PIK3CA-expressing vector and verified the expression of PIK3CA by qRT-PCR and Western blot." (PMID 33344221, 2020). "According to literature research, this is the first study demonstrating that PIK3CA expression is positively correlated with CUX1 in bladder cancer cells." (PMID 33344221, 2020). "Accumulated evidence has exhibited that genetic changes act as a vital role in the carcinogenesis and metastasis of bladder cancer, including changes in genes, such as PIK3CA, NPR3, and FGFR3, as well as non-coding RNAs, such as mir-93, mir-106b." (PMID 33344221, 2020). "Significantly, restoration of PIK3CA expression rescued bladder cancer cells from CUX1-knockdown inhibition of growth, aggressiveness, and angiogenesis." (PMID 33344221, 2020). "In conclusion, these findings indicated that the tumor promoting roles of PIK3CA through regulatory effects on proliferation, migration, invasion, and angiogenesis of bladder cancer cells." (PMID 33344221, 2020). "The findings revealed that PIK3CA rs6443624 C>A and AKT1 rs2498801A>G variants caused a significant decline in the risk developing bladder cancer." (PMID 29383014, 2018). "A large fraction of bladder cancers displays alterations in PI3K pathway components, including PIK3CA gene mutations frequently associated to low grade and stage tumors." (PMID 28060766, 2017). "To date, the relevance of PIK3CA alterations in bladder cancer recurrence remains poorly understood." (PMID 28060766, 2017). "One patient had bladder cancer with PIK3CA H1047L and was treated at dose level 4; however, he discontinued therapy because of worsening renal function (> grade 3) and was not evaluable for response." (PMID 27589687, 2016). "Although PIK3CA alterations are common in bladder cancer, their prognostic significance is unclear and may depend on interactions with other genetic alterations." (PMID 39410541, 2024). "The PIK3CA is overexpressed in bladder cancer and its expression is regulated by CUX1." (PMID 37627900, 2023). "CUX1 upregulates PIK3CA expression in bladder cancer and this in turn, further activates EMT." (PMID 37627900, 2023). "PIK3CA promotes bladder cancer cell proliferation, migration, invasion, and angiogenesis in vitro." (PMID 37627900, 2023). "While genes such as FGFR3 and PIK3CA may have a high frequency in the early stages of bladder cancer, and are still detectable, they are outcompeted by cells with driver mutations associated with MIBC." (PMID 37175559, 2023).
bladder cancer (continued). "Therefore, although PIK3CA is a valuable therapeutic target for inhibitors of PI3K/AKT/mTOR pathways in advanced bladder cancer, the detailed expression status of the mutations should be carefully evaluated when the targeted therapy is considered." (PMID 35846154, 2022). "The tendency of mutual exclusivity between AHR, FGFR3, and PIK3CA alterations may indicate convergence on the same pathway, although a fully independent parallel oncogenic pathway in bladder cancer driven by AHR cannot be excluded." (PMID 35710704, 2022). "Of course, we will further explore the relationship between CUX and PIK3CA in bladder cancer." (PMID 33344221, 2020). "PIK3CA has been reported in higher frequency in endometrial, breast and bladder cancers." (PMID 33167967, 2020). "We will collect the tumor samples from patients with bladder cancer and the relationship between loss of PTEN and the mutation of PIK3CA can be observed by “Next-generation” sequencing technology (NGS) sequencing, laying a foundation for the treatment of bladder cancer." (PMID 33344221, 2020). "At the same time, our current findings suggest that PIK3CA may be related to EMT in regulating the occurrence and development of bladder cancer, but how PIK3CA regulates the dynamic process of EMT requires further research in the future." (PMID 33344221, 2020). "However, the detailed mechanism of TF function in regulating PIK3CA in bladder cancer is complex and not well understood." (PMID 33344221, 2020). "However, the potential mechanism of CUX1 regulation of PIK3CA in bladder cancer cells requires further investigation." (PMID 33344221, 2020). "Tissue microarray (TMA) with 66 bladder cancer patients was surveyed via immunohistochemistry to evaluate the level of PIK3CA and CUX1 and we found upregulation of PIK3CA in bladder cancer tissue and patients with higher level of PIK3CA presented with poorer prognosis." (PMID 33344221, 2020). "ChIP assay indicated that binding to the PIK3CA promoter could be increased or decreased with overexpression or knockdown of CUX1 in bladder cancer cells, respectively." (PMID 33344221, 2020). "Therefore, more studies are required to further investigate how PIK3CA act in bladder cancer development and progression." (PMID 33344221, 2020). "PIK3CA-mutated bladder cancer patient-derived xenografts (PDXs) have a non-T-cell-inflamed phenotype, while the administration of BKM120, a pan PI3K inhibitor, induces immune activation and the response to PD-1 inhibitors." (PMID 32575899, 2020). "It is entirely possible that PIK3CA may also be involved in the progression of bladder cancer through other regulatory pathways." (PMID 33344221, 2020). "Finally, Kaplan–Meier survival curves of 53 cases of bladder cancer patients derived from the TMA showed that patients with high expression of PIK3CA (n = 39) exhibited significantly worse survival as compared to those with low expression (n = 14) (P < 0.001)." (PMID 33344221, 2020). "Moreover, dual-luciferase reporter assay demonstrated that up-regulation of CUX1 facilitated the transcription activity of PIK3CA in bladder cancer cells." (PMID 33344221, 2020). "PIK3CA functions to promote proliferation and metastasis of bladder cancer by activating EMT." (PMID 33344221, 2020). "This suggests that CUX1 may exert its tumor promoting function through transcriptional regulation of PIK3CA in bladder cancer." (PMID 33344221, 2020). "Furthermore, the expression of PIK3CA is an independent favorable prognostic factor for bladder cancer patients." (PMID 33344221, 2020). "However, more detailed analysis of the molecular mechanisms of PIK3CA-related functions in bladder cancer is still in urgent need." (PMID 33344221, 2020).